STAT2 (signal transducer and activator of transcription 2)
Diseases named in the same sentence as STAT2 in open-access papers (continued):
Sharing a sentence is not in itself a finding about the gene and the disease.
cancer (continued). "The activated JAK1 and TYK2 in turn phosphorylate STAT1 and STAT2 setting in motion a cascade of events which finally initiates the transcription of IFN-inducible genes switching on the anti-cancer and anti-viral effects as reviewed in Randall and Goodbourn." (PMID 28344639, 2017). "Inhibition of HSP27 has been reported to induce the degradation of the histone deactylase HDAC6, transcription factor STAT2 and procapase-3 in human cancer cells." (PMID 23555679, 2013). "Of interest, the expression patterns of STAT1 and STAT2 were variable in various cancer types." (PMID 38191598, 2024). "Moreover, KO cells demonstrated substantially altered transcription factor motifs, e.g., Stat1, Stat2, and Irf/Nfkb, suggesting enhanced cancer immunogenicity at the epigenetic level." (PMID 39255035, 2024). "Like STAT2 and STAT4, the role of STAT6 remains largely unknown, though there is some evidence that STAT6 is associated with supporting the cancer stem cell niche in OvCa." (PMID 37173951, 2023). "Here, we report a protumor function of STAT2 that inhibits the activation of STING in cancer cells." (PMID 37036972, 2023). "STAT2 also contributes to tumorigenesis in various types of cancer." (PMID 37036972, 2023). "Actually, previous studies have suggested STAT2 as biomarker for many cancers." (PMID 37115061, 2023). "To investigate whether STAT2 interferes with cell death induced by anti-cancer drugs triggering other mechanisms, we performed additional experiments focusing on 5-Fluorouracil." (PMID 38001683, 2023). "Moreover, due to the deficiency in our understanding of STAT1, STAT2, STAT4, and STAT6 in cancer, selective inhibitors also remain elusive." (PMID 37173951, 2023). "Considering the controversial roles of STAT2, our study might provide further clarifications with respect to the role of STAT2 in cancer." (PMID 35946310, 2022). "We hypothesized that STAT2 (signal transducer and activator of transcription 2) could directly bind at open chromatin regions of the PD-L1 promoter and regulate PD-L1 expression in cancer cells." (PMID 35946310, 2022). "Therefore, it would be interesting to investigate the role of STAT1 and STAT2 as well as KPNA1 in radiation-increased KPNB1-mediated IRF1 expression in these cancers." (PMID 34069326, 2021). "Our in silico analysis using TCGA cohort revealed correlations between IRF1 and STAT1 or STAT2 mRNA in HNSCC and LUAD, suggesting that STAT1 and/or STAT2 may be mainly involved in PD-L1 expression in these cancers." (PMID 34069326, 2021). "In relation to cancer, slow growth induced by FLCN loss and STAT2 upregulation may form a barrier to TFE3-driven renal tumorigenesis in BHD patients." (PMID 33459596, 2021). "While STAT1 and STAT2 primarily drive immune signalling initiated by interferons, STAT3 and STAT5 have widely been linked to the survival and proliferative potential of a number of cancers." (PMID 32899142, 2020). "Moreover, the STAT2-mediated NF-κB signaling pathway additively supports carcinogenesis and cancer therapeutic drug resistance." (PMID 32973222, 2020). "In addition, treatment with PYR41, a ubiquitin-activating enzyme E1 inhibitor, and MLN4924, an E3 ligase inhibitor, did not decrease total levels of p-STAT1/2, but markedly reduced the cytosolic p-STAT2 puncta as well as p-STAT1/2 levels in LEVs from USP5-depleted cancer cells." (PMID 41321309, 2025). "Studies have shown that human infant TNFSF13B is the most demethylated gene in the TNFSF family, with a 20% decrease in β after birth; STAT2 plays an important role in the immune response to intracellular and extracellular stimuli, including in inflammation, foreign substance invasion, and cancer." (PMID 39202427, 2024). "Importantly, the lack of STAT2 increased the susceptibility of intestinal tumoroids to cell death induced by different anti-cancer drugs that kill by engaging non-overlapping molecular mechanisms." (PMID 38001683, 2023).
cancer (continued). "Thus, via in vitro experiments, we validated that overexpression of STAT2 could upregulate PD-L1 expression in cancer cells, which was in line with the results of the bioinformatics analysis." (PMID 35946310, 2022). "Furthermore, both CXCL10 and STAT2 are involved in the induction of apoptosis in cancer cells." (PMID 35207629, 2022). "Thus, we hypothesized that the combination treatment targeting STAT2 might increase the efficacy of anti-PD-1/PD-L1 treatment in patients diagnosed with this cancer subtype." (PMID 35946310, 2022). "Moreover, STAT2 is highly expressed or abnormally activated in multiple types of cancer and promotes malignant biological behaviors, including the proliferation, migration, invasion, and epithelial-to-mesenchymal transition of cancer cells." (PMID 33110456, 2020). "A key mediator is IGFBP2, upregulated in several cancers and involved in processes such as EMT, angiogenesis, and invasion via β-catenin and STAT2 signaling, contributing to the malignancy." (PMID 41226816, 2025). "We further treated THP1-MΦ with LEVs isolated from STAT2-EGFP–transfected and IFN-β–treated cancer cells." (PMID 41321309, 2025). "We confirmed the activation of IFN‐I signaling in cancer cells with MSC‐DC, as reflected by increased phosphorylation of STAT1 and STAT2 and increased IRF9 expression, which was reduced by Gap26." (PMID 38638003, 2024). "It remains to be addressed by further studies, using tissue-specific conditional deleters, how various cell types employ STAT2 and STAT3 signals to control discrete functions in normal (i.e., organoid) vs. cancer (i.e., tumoroid) epithelium." (PMID 38001683, 2023). "More importantly, it is clear that other STAT family members—STAT1, STAT2, STAT4, and STAT6—also contribute critical roles to cancer progression, either modulating the cancer cell directly or by altering cells of the TME." (PMID 37173951, 2023). "We found higher levels of epithelial stem cell/cancer stem cell markers (e.g., Lgr5, Axin2, Cd44, Prom1/CD133) in the tumoroids derived from ApcMin/+ WT as compared with ApcMin/+ Stat2−/− mice." (PMID 38001683, 2023). "We investigated the role of STAT2 in CRC using experimental mouse models coupled with RNA-sequencing (RNA-Seq) data and functional assays with anti-cancer agents in three-dimensional tumoroids." (PMID 38001683, 2023). "Historically, there are limited numbers of reports relating STAT2 and STAT4 dysregulation with the clinical characteristics and prognosis of human cancer." (PMID 36176415, 2022). "Work in both normal and cancer cells demonstrated that IRF9 can assemble with unphosphorylated STAT1 and STAT2 to form the unphosphorylated ISGF3 (U-ISGF3) complex." (PMID 35244540, 2022). "The gene of STAT genes was altered in 1,003 (9%) samples; STAT1, STAT2, STAT3, STAT4, STAT5A, STAT5B, andSTAT6 were altered in 2.3%, 1.7%, 2.0%, 2.4%, 1.6%, 1.9%, and 1.9% of the demanded pan-cancer samples." (PMID 36176415, 2022). "Along with STAT2, STAT1 induces IFN-regulated genes, enhances antigen presentation, and contributes to an inflammatory, anti-cancer response." (PMID 36276148, 2022). "Most of the activated TFs are involved in cancer progression through the TIME, such as the NFκB family (NFKB1, NFKBIA, and RELA) and the STAT family (STAT1, STAT2, and STAT6), which are critical in M1 and M2 macrophage polarization." (PMID 36230879, 2022). "It is important to differentiate STAT1 and STAT2 from other STAT family members such as STAT3 and STAT5, which contribute to cancer cell survival, proliferation, and angiogenesis." (PMID 36276148, 2022).
cancer (continued). "In carcinomas, constitutive STAT3 activation also reduces the expression of ISGF3 components (such as IRF9, STAT1, and STAT2) and IRF7, a transcription factor that participates in IFN response-related gene expression by directly binding to gene promoters." (PMID 36358904, 2022). "Of the rest, CPEB4, MCM4, RNF4, STAT2, and WEE1 were also shown to correlate with a number of cancer types." (PMID 27418131, 2016). "We therefore suggest taking STAT2 protein expression into account when assessing STAT1 bioactivity, including as predictor of prognosis in cancer and disease development." (PMID 27780205, 2016). "Besides STAT1 and STAT2, other components of the JAK/STAT pathway have been studied in the pathogenesis of cancer, including STAT3." (PMID 39405604, 2024). "In the present study, FOXA1 was found to be upregulated and has been reported to inhibit STAT2, a transcription factor and its target IFN signaling pathway in BC; this may result in cancer progression due to suppressed immune response." (PMID 37900178, 2023). "In addition, IFN-λ acted together with related genes such as STAT1, STAT2, and STAT3 affecting the JAK-STAT signaling pathway to promote cancer progression." (PMID 37697300, 2023). "In addition, the distribution of STAT1, STAT2, STAT3, STAT4, STAT5A, STAT5B, and STAT6 expression in CD8+ T cells in pan-cancer were displayed, which presented that STAT1 and STAT2 had prominent up-regulation in CD8+ T cell with ISG IFIT1." (PMID 36968603, 2023). "The intricate mechanisms through which STAT2-mediated signals control resistance to anti-cancer drugs have not been further addressed in our study, and thus remain a subject for future endeavors." (PMID 38001683, 2023). "Conversely, STUMPs and LMSs shared 47 CNAs, in particular gain/amplification of the regions containing cancer related genes as PRKDC (8q11.21; eight samples), MLL3 (7q36.1; seven samples), ROCK2 (2p25.1; six samples), CTSB (8p23.1; six samples) and STAT2 (12q13.2; five samples)." (PMID 33557274, 2021). "STAT2 and STAT4 remain nearly unresearched in PCa but could potentially be of interest as studies in other malignancies showed their involvement in cancer progression as well as suppression." (PMID 34638338, 2021). "TEAD-AP1 cooperation with steroid receptor coactivators (SRC) drives downstream gene transcription to regulate cancer cell migration and invasion, and STAT1, STAT2 and IRF9 form a heterotrimer that regulates transcription of genes containing IFN-stimulated response elements." (PMID 27899659, 2017). "Furthermore, human cancer cell lines expressing STAT2, a constituent of the complex, are more resistant to radiotherapy than those that do not express STAT2." (PMID 38474078, 2024). "Yet, a direct role for USP18 in transcription regulation has not been reported, but it might form a complex with STAT2/STAT1/IRF9 to enhance expression of ISGs in cancer cells." (PMID 37002195, 2023). "Additionally, the distribution of STAT1, STAT2, STAT3, STAT4, STAT5A, STAT5B, and STAT6 expression in CD4+ T cells in pan-cancer were also clearly illustrated, which showed that STAT1 and STAT2 expression were notably up-regulated in CD4+ Treg cell with marker OSA1 and CD4+ T cell with ISG IFIT1." (PMID 36968603, 2023). "Previous reports suggest that STAT2, like STAT1, may play a dual role in cancer progression." (PMID 36061181, 2022). "Signal transducer and activator of transcription (STAT2) is a member of the STAT family that plays an essential role in immune responses to extracellular and intracellular stimuli, including inflammatory reactions, invasion of foreign materials, and cancer initiation." (PMID 32973222, 2020). "Thus immune cells have much higher expression of ISGF3 subunits STAT2 and IRF9 than that in kidney cancer cells, and this could disrupt the detection of ISGF3 mRNA expression in the cancer cells." (PMID 30355451, 2018).
cancer (continued). "STAT2 depletion in USP5-deficient cancer cells significantly reduced upregulated CXCL9 and CXCL10 mRNA, as well as CD86 and HLA-DR protein of cocultured THP1-MΦ; these reductions were rescued by restoring WT-STAT2 but not the Y690A mutant in USP5-depleted cells." (PMID 41321309, 2025). "Through the isolation of large EVs (LEVs) and classical exosomes from culture medium, we found p-STAT1 and p-STAT2 in LEVs, but not in classical exosomes, from USP5-depleted cancer cells after IFN-β treatment." (PMID 41321309, 2025). "Currently, based on our literature search, there are no selective inhibitors for STAT2 or STAT4, and yet STAT2 and STAT4 enhance cancer progression by promoting EMT." (PMID 37173951, 2023). "STAT2 binds to STING, modulating its function by inhibiting the expression of IRF3-dependent antitumor genes, but not of NF-κB–dependent protumor genes, thus helping cancer cells to resist DNA damage." (PMID 37036972, 2023).
bacterial infection (4 papers, 2018 to 2023). "In our study, we also show an increase of STAT1 as a key regulator of monocyte differentiation, and STAT2 has been associated with dysregulation of macrophage phenotype during viral or bacterial infection." (PMID 37692050, 2023). "In addition, a further 12 ISGs of 380 tested ISGs including STAT1, STAT2, JAK1, IRF9, IRF2, IRF7 are key elements of IFN signaling, and classical and well-known ISGs such as ISG15, PKR, MX1, IFIT1, PML, IFI27 play key roles in viral or bacterial infections." (PMID 30717477, 2019).
infectious disease (4 papers, 2015 to 2021). A disorder directly resulting from the presence and activity of a microbial, viral, or parasitic agent in humans. "Of note, although IRF1 signals are essential for infectious diseases and for the inflammatory response of TLR4, IRF1, NF-κB2 and STAT2 were predicted to exhibit higher activation under TLR3 stimulation." (PMID 26159724, 2015).
inflammation (1 paper, 2025). Aberrant reaction of the microcirculation characterized by movement of fluid and leukocytes from the blood into extravascular tissues. "METTL3 exacerbates LPS-induced pulmonary inflammation by mediating m6A methylation of STAT2 mRNA to enhance its stability and translation, thereby activating inflammatory responses and aggravating lung injury." (PMID 41105618, 2025).
mitochondrial disease (1 paper, 2015). "Whole exome sequencing did not demonstrate any pathogenic mutations in known or putative mitochondrial disease genes in these siblings, but did reveal a novel homozygous stop-gain mutation c.1836 C > A (p.Cys612Ter) in STAT2, located within the region of extended homozygosity on chromosome 12." (PMID 26122121, 2015).
neurodegenerative disease (1 paper, 2017). A disorder of the central nervous system characterized by gradual and progressive loss of neural tissue and neurologic function. "Thus, the down-regulation of STAT1, STAT2, IRF7 and IRF9 through GSK-J4 could inhibit neurodegenerative diseases as well as brain inflammation." (PMID 28747667, 2017).
STAT2 also shares sentences with these, for which no sentence is quoted: diabetes (4 papers); pneumonia (4); viral disease (4); gastric cancer (3); lupus (3); Obesity (3); osteosarcoma (3); primary immunodeficiency (3); rubella (3); adenocarcinoma (2); Brain atrophy (2); brain tumor (2); breast tumor (2); cervicitis (2); cognitive defects (2); head and neck cancer (2); Hepatitis (2); metabolic disease (2); mumps (2); neurological disorders (2); non-small cell lung carcinoma (2); type 2 diabetes (2); abdominal aortic aneurysm (1); acute respiratory distress syndrome (1); adenoma (1); aneurysm (1); ankylosing spondylitis (1); atrial fibrillation (1); atrophic gastritis (1); autoimMune (1).
A further 70 diseases each share a sentence with STAT2 in 1 paper.